ACADSB (acyl-CoA dehydrogenase short/branched chain)
Description:
Short and branched chain specific acyl-CoA dehydrogenase that catalyzes the proR-proR stereospecific alpha,beta-dehydrogenation of fatty acyl-CoA thioesters using the electron transfer flavoprotein (ETF) as their physiologic electron acceptor, resulting in the formation of trans-2-enoyl-CoA ((2E)-enoyl-CoA). Among the different mitochondrial acyl-CoA dehydrogenases, acts specifically on short and branched chain acyl-CoA derivatives such as (S)-2-methylbutyryl-CoA as well as short straight chain acyl-CoAs such as butyryl-CoA (butanoyl-CoA). Plays an important role in the metabolism of L-isoleucine by catalyzing the dehydrogenation of 2-methylbutyryl-CoA, one of the steps of the L-isoleucine catabolic pathway. Can also act on valproyl-CoA, a metabolite of valproic acid, an antiepileptic drug.
Synonyms: SBCAD; 2-MEBCAD; ACAD7
Tractability: Small molecule: a structure with a bound ligand is known; it has a high-quality binding pocket. PROTAC: ubiquitination databases record sites on it; its protein half-life has been measured.
Gene: Protein-coding gene on chromosome 10 (123,008,972 to 123,058,290, forward strand). Ensembl gene ENSG00000196177.
Subcellular location: Mitochondrion matrix
Subcellular location (Human Protein Atlas): Mitochondria
Pathways (Reactome):
Metabolism: Branched-chain amino acid catabolism
Metabolism of proteins: Mitochondrial protein degradation
Gene Ontology:
Molecular function: identical protein binding; short-chain 2-methyl fatty acyl-CoA dehydrogenase activity; short-chain fatty acyl-CoA dehydrogenase activity; acyl-CoA dehydrogenase activity; flavin adenine dinucleotide binding; medium-chain fatty acyl-CoA dehydrogenase activity; oxidoreductase activity, acting on the CH-CH group of donors
Biological process: fatty acid metabolic process; L-isoleucine catabolic process; carboxylic acid catabolic process
Cellular component: mitochondrion; mitochondrial matrix
Genetic constraint (gnomAD): Loss-of-function variants: 29 observed, 44.38 expected, observed/expected ratio (o/e) 0.65, 90% interval 0.49 to 0.89. The upper end of that interval is the gene's LOEUF score, 0.89, which puts it in group 3 of 6, group 1 being the genes least tolerant of losing a copy. Missense variants: 512 observed, 505.79 expected, observed/expected ratio (o/e) 1.01, 90% interval 0.94 to 1.09. Synonymous variants: 171 observed, 182 expected, observed/expected ratio (o/e) 0.94, 90% interval 0.83 to 1.07.
Gene-disease validity (ClinGen):
ClinGen rates the evidence that ACADSB causes each of these diseases.
2-methylbutyryl-CoA dehydrogenase deficiency (autosomal recessive): Definitive. A rare organic aciduria characterized by impaired isoleucine degradation with increased plasma or whole blood C5 acylcarnitine levels (typically observed in newborn screening) and increased urinary excretion of N-methylbutyrylglycine.
Homologues: Orthologues: chimpanzee ACADSB (98% identical), macaque ACADSB (95% identical), rabbit ACADSB (88% identical), rat Acadsb (82% identical), mouse Acadsb (82% identical), dog ACADSB (82% identical), guinea pig ACADSB (81% identical), pig ACADSB (79% identical), tropical clawed frog acadsb (68% identical), zebrafish acadsb (64% identical), Drosophila melanogaster CG3902 (54% identical), Caenorhabditis elegans acdh-1 (51% identical), and 8 more. Paralogues in human: ACADS (37% identical), ACAD9 (34% identical), ACADM (34% identical), ACAD8 (32% identical), ACADVL (32% identical), IVD (32% identical), GCDH (29% identical), ACADL (29% identical), ACAD10 (25% identical), ACAD11 (24% identical), ACOX3 (23% identical), ACOX2 (20% identical), and 2 more.
Diseases named in the same sentence as ACADSB in open-access papers:
ACADSB is named in the same sentence as 39 diseases in open-access papers, as found by Europe PMC text mining. Sharing a sentence is not in itself a finding about the gene and the disease. The quoted sentences say what the papers report.
2-methylbutyryl-CoA dehydrogenase deficiency (6 papers, 2019 to 2026). "Short/branched-chain acyl-CoA dehydrogenase deficiency (SBCADD) is an inherited disorder of L-isoleucine metabolism due to mutations in the ACADSB gene." (PMID 36147814, 2022). "Short/branched chain acyl-CoA dehydrogenase deficiency (SBCADD) is an autosomal recessive disorder of impaired isoleucine catabolism caused by mutations in the ACADSB gene." (PMID 31555323, 2019). "Short/branched chain acyl-CoA dehydrogenase (SBCAD) deficiency is a genetic disorder (ACADSB gene) which can manifest as symptomatic in a small subgroup of patients (approx. 10%) with neurological symptoms, including developmental delay, hypotonia, and autism, having been reported." (PMID 31766743, 2019). "Short/branched-chain acyl-CoA dehydrogenase (SBCAD) deficiency (SBCADD) (OMIM# 600301, also known as 2-methylbutyrylglycinuria, OMIM#610006) is an autosomal recessive metabolic disorder due to mutations in the ACADSB gene." (PMID 36147814, 2022).
colorectal cancer (6 papers, 2021 to 2025). A primary or metastatic malignant neoplasm that affects the colon or rectum. "Previous studies have shown that ACADSB plays an important role in glioma, colorectal cancer, hepatocellular carcinoma, clear cell renal cell carcinoma and non‐small cell lung cancer." (PMID 41340014, 2025). "Previous studies have revealed that ACADSB plays an important role in glioma, colorectal cancer (CRC), and hepatocellular carcinoma (HCC)." (PMID 35096573, 2021). "Recent studies have found that ACADSB plays an important role in the development and progression of malignant diseases, such as glioma, colorectal cancer, and hepatocellular carcinoma (HCC)." (PMID 35096573, 2021). "Studies have demonstrated that the expression of ACADSB is negatively correlated with colorectal cancer stage; ACADSB expression is also negatively correlated with stage and grade in clear cell renal cell carcinoma and is an independent factor of overall survival." (PMID 41187148, 2025). "Acyl-CoA Dehydrogenase Short/Branched Chain (ACADSB) negatively regulates the expression of GPX4 and enhances the accumulation of Fe2+ and lipid peroxidation in colorectal cancer cells, thereby inducing ferroptosis." (PMID 40721409, 2025). "Several colorectal cancer studies have tested RSL3, resibufogenin, bromelain, apatinib, ACADSB, IMCA, and a slew of other ferroptosis inducers and inhibitors." (PMID 39031216, 2024).
breast carcinoma (4 papers, 2021 to 2024). "Proteome data derived from the UALCAN database also suggest that ACADSB is down-regulated in breast cancer, colon cancer, ccRCC, and UCEC." (PMID 35096573, 2021). "In breast cancer, MRPS31 is overexpressed in metastatic cell lines (MDA-MB231, MDA-MB468), and is known to interact with ACADSB [ACADSB is involved in fatty acid oxidation and has been associated with EMT and progression in a range of cancers, including breast cancer]." (PMID 39354291, 2024).
glioma (3 papers, 2020 to 2025). A benign or malignant brain and spinal cord tumor that arises from glial cells (astrocytes, oligodendrocytes, ependymal cells). "As shown in the LRS formula, the expression of GNAI3, ACACB, ADCY3, and ACADSB emerged as the most important LMRGs that contribute to the risk signature of gliomas patients." (PMID 36860853, 2023). "Consistently, the protein expression of GNAI3 was higher in the more aggressive high-grade gliomas in the Human Protein Atlas immunohistology study, while that of ACADSB exhibited a reverse trend." (PMID 36860853, 2023). "Combined with gene expression data from TCGA database, lower ACADSB responsible for the elevated short-chain acylcarnitines was found to be strongly related to glioma progression." (PMID 33255474, 2020). "Furthermore, the gene expression of short/branched-chain acyl-coenzyme dehydrogenase (ACADSB), which is involved in fatty acid oxidation, was found down-regulated with glioma progression by analyzing related genes and pathways." (PMID 33255474, 2020).
hepatocellular carcinoma (3 papers, 2021 to 2025). A malignant tumor that arises from hepatocytes. "It has been reported that ACADSB is low expressed in poorly differentiated hepatocellular carcinoma cells." (PMID 34868460, 2021).
Obesity (2 papers, 2020 to 2024). Accumulation of substantial excess body fat. "A total of 12 significant SNPs associated with BMI were identified, of which 7 SNPs were also significantly associated with obesity, including rs1337406 (WLS), rs673612 (NTNG1), rs4449107 (FAM84A), rs9820485 (STAG1), rs73247924 (CCKAR), rs2083069 (ACADSB), and rs4942190 (DNAJC15)." (PMID 38807991, 2024). "Increases in the mRNA levels of ACADSB, BCAT2, HADHA and both the A and B subunits of BCKDH suggested that BCAA catabolism is upregulated in the AA of obese cardiac surgery patients and particularly pronounced in class III obesity." (PMID 32903728, 2020). "Similarly, reduced ACADSB and HADH mRNA levels were also correlated with increased hip circumference, suggesting that in the SAT, BCAA catabolic enzymes are downregulated in the setting of obesity." (PMID 32903728, 2020).
bile acid synthesis disorder (1 paper, 2025). "Druggability evaluation highlighted four protein biomarkers, ITGB2, GP1BA, ACADSB and COX6B1, which are already targeted for dry eye disease, inflammation, seizure and bile acid synthesis disorder, respectively." (PMID 41340014, 2025).
complex partial seizures (1 paper, 2025). "Valproic acid, targeting ACADSB, has been developed to control complex partial seizures and absence seizures." (PMID 41340014, 2025).
developmental delay (1 paper, 2021). "The clinical manifestations of ACADSB- and VLCAD-deficiency can vary, such as developmental delay, muscular atrophy, hypotonia, and myasthenia gravis." (PMID 33920575, 2021).
diabetes (1 paper, 2018). "Both meta-analyses presented consistent tests of DGE and the results showed that genes of ACADSB, RASSF2, and KLF12 had significant gene expression associations with diabetes traits." (PMID 29503662, 2018). "The analysis showed that six gene sets and three member genes of ACADSB, RASSF2, and KLF12 had significant associations with diabetes traits." (PMID 29503662, 2018).
diabetic cardiomyopathy (1 paper, 2024). Diabetic cardiomyopathy is a disorder of the heart muscle in people with diabetes. "We constructed a diagnostic model of DCM, and OXCT1, CACNA2D2, BCL7B, EGLN3, GABARAP, and ACADSB were potential biomarkers, which may provide new insights for improving the ability of early diagnosis and treatment of diabetic cardiomyopathy." (PMID 38469146, 2024). "We found diagnostic and predictive biomarkers of type 2 DCM consisting of OXCT1, CACNA2D2, BCL7B, EGLN3, GABARAP, and ACADSB, which may reduce the difficulty of early prediction of diabetic cardiomyopathy, and lay a foundation for prospective research." (PMID 38469146, 2024).
liver cancer (1 paper, 2025). An epithelial or non-epithelial malignant neoplasm that arises from the liver. "Liver cancer patients with low ACADSB expression have poor survival outcomes." (PMID 41187148, 2025).
lung adenocarcinoma (1 paper, 2022). A carcinoma that arises from the lung and is characterized by the presence of malignant glandular epithelial cells. "The low expression of several enzymes, such as BCKDHB, ACADSB and HMGSC2, was correlated with worse patient survival in lung adenocarcinomas." (PMID 36433955, 2022).
lung carcinoma (1 paper, 2025). "Druggability evaluation suggests that existing drugs targeting ITGB2, GP1BA, ACADSB and COX6B1 could potentially be repurposed for the treatment of specific lung cancer subtypes." (PMID 41340014, 2025). "Additionally, the repurposing of approved drugs targeting ITGB2, GP1BA, ACADSB and COX6B1 for the treatment of different lung cancer subtypes provides new therapeutic options, potentially leading to more effective treatments for patients with advanced lung cancer." (PMID 41340014, 2025).
mesothelioma (1 paper, 2021). A usually malignant and aggressive neoplasm of the mesothelium which is often associated with exposure to asbestos. "In addition, Kaplan–Meier analysis indicated that low expression of ACADSB is associated with poor prognosis in BRCA luminal subtype, COAD, KIRC, brain lower grade glioma (LGG), and mesothelioma (MESO)." (PMID 35096573, 2021).
renal carcinoma (1 paper, 2022). A carcinoma arising from the epithelium of the renal parenchyma or the renal pelvis. "Thus, this study selected IYD, ACADSB, and PSAT1 for validation since they had not been validated in renal cancer tissues and cell lines." (PMID 36118874, 2022).
small cell carcinoma (1 paper, 2025). A neuroendocrine carcinoma composed of small malignant cells which are often said to resemble "oat cells" under the microscope. "Tier 1 proteins passed all evaluations, including GP1BA (squamous cell carcinoma) and ACADSB (small cell carcinoma)." (PMID 41340014, 2025).
small cell lung carcinoma (1 paper, 2025). Small cell lung cancer (SCLC) is a highly aggressive malignant neoplasm, accounting for 10-15% of lung cancer cases, characterized byrapid growth, and early metastasis. "For small cell lung cancer, ACADSB, CEACAM6, COX6B1, CPXM2 and IL12RB2 continued to show significant associations." (PMID 41340014, 2025). "Our study identified five candidate proteins for small cell lung cancer: ACADSB, CEACAM6, COX6B1, CPXM2 and IL12RB2." (PMID 41340014, 2025). "Specifically, ACADSB, which was further validated through bulk transcriptomic analyses, may play a crucial role in small cell lung cancer pathogenesis and could be a promising target for precision medicine." (PMID 41340014, 2025). "However, the association of ACADSB with small cell lung cancer has not yet been reported." (PMID 41340014, 2025).
tumor (12 papers, 2015 to 2025). "Clinical association analysis indicated that decreased ACADSB expression was associated with high tumor stage and grade." (PMID 35096573, 2021). "As the results indicated, the expressions of CDCA3, MYCN and TFAP2A in ccRCC tumor tissue were significantly upregulated compared with those in adjacent normal kidney tissue, while the expressions of ACADSB and CHAC1 were significantly downregulated." (PMID 37064095, 2023). "The expression level of ACADSB was positively correlated with tumor purity and the infiltration levels of CD4+ T cells, dendritic cells, and neutrophil, but not with the infiltration levels of CD8+ T cells, B cells, and dendritic cells." (PMID 34868460, 2021). "Both CMPK1 and ACADSB seem to be vital to tumor cell growth in HCC models with a lower survival rate." (PMID 33424926, 2020). "The downregulation of ACADSB might promote tumorigenesis and tumor progression by inhibiting FA catabolism, BCAA catabolism, and ferroptosis in ccRCC." (PMID 35096573, 2021). "The differential expression analyses were performed in three independent datasets, and consistent results were obtained, indicating that ACADSB is down-regulated in ccRCC, and that ACADSB expression can be a single significant parameter to discriminate between normal and tumor tissues." (PMID 35096573, 2021). "Differential expression analyses revealed that ACADSB was down-regulated in ccRCC, indicating that ACADSB expression could be a single significant parameter to discriminate between normal and tumor tissues." (PMID 35096573, 2021). "Taken together, ACADSB might also be a potential ferroptosis driver gene, and the downregulation of ACADSB in ccRCC may promote tumor progression by suppressing ferroptosis." (PMID 35096573, 2021). "Moreover, we were able to validate the expression of 16/57 differentially expressed proteins in MDCKYBX1 tumour xenografts, some of which were mitochondrial (ACADSB, SLC25A1, IARS2, and OAT)." (PMID 25980435, 2015). "Thus, the downregulation of ACADSB may contribute to tumor development by suppressing FA catabolism, resulting in lipid accumulation in ccRCC." (PMID 35096573, 2021). "Further, ROC analyses showed that ACADSB expression could be a single significant parameter for discriminating between normal and tumor tissues in TCGA-KIRC (AUC = 0.952, 95% CI = 0.926–0.977), GSE36895 (AUC = 0.931, 95% CI = 0.862–1.0), and GSE53757 (AUC = 0.966, 95% CI = 0.935–0.998)." (PMID 35096573, 2021). "Therefore, the downregulation of ACADSB may also promote tumor development and growth by inhibiting BCAA catabolism." (PMID 35096573, 2021). "The expression levels of ACADL, ACADS, ACADSB, ALDH6A1, ETFDH, and GCDH were found to be lower in tumor samples compared to normal samples, whereas the expression levels of CCNB1 and CDK1 were observed to be higher in tumor than in normal samples." (PMID 37994323, 2023). "Furthermore, exploration of enzymes revealed that ACADSB (which was also highlighted by previous analyses), ACSL3, and ACSL4 regulate proteins that stimulate tumor cell proliferation, including p-AKT, LSD1, and β-catenin." (PMID 33424926, 2020). "Some adhesion molecules play an important role in tumor recurrence, metastasis, and invasion.(Okegawa, Pong, Li, & Hsieh, 2004) Based on the construction of PPI network and module analysis, ACAA1, ACADSB, ALDH6A1, AUH, HADH,and PCCA with high degree of connectivity were selected as hub genes." (PMID 30793530, 2019).
cancer (7 papers, 2014 to 2025). A tumor composed of atypical neoplastic, often pleomorphic cells that invade other tissues. "In conclusion, ACADSB is down-regulated in multiple types of cancers and shows good diagnostic and prognostic abilities in ccRCC." (PMID 35096573, 2021). "In this study, we first explored the expression levels of ACADSB in different types of cancer using independent datasets from TCGA and UALCAN." (PMID 35096573, 2021). "Pan-cancer analysis revealed that ACADSB is down-regulated in multiple cancers, and decreased expression of ACADSB correlates with poor prognosis in certain types of cancer." (PMID 35096573, 2021). "Moreover, low expression levels of ACADSB also correlate with a poorer prognosis in many types of cancers, such as COAD, LGG, and ccRCC." (PMID 35096573, 2021). "The downregulation of ACADSB was observed in almost all types of common cancer." (PMID 35096573, 2021). "PPAR signaling pathway has been previously reported to be regulated by NAT10 through ac4C modification of genes such as ELOVL6, ACSL1, ACSL3, ACSL4, ACADSB, and ACAT1, thus modulating fatty acid metabolism in cancer cells." (PMID 40123006, 2025). "It is known that the roles of ACADSB, ACADM, HADH, PYCR1 and ITPKA have been explored in cancers, whereas PAFAH2 not12–16." (PMID 37460577, 2023). "The results of RT-PCR in tissues demonstrated that IYD, ACADSB, and PSAT1 had significantly lower expression levels in cancer tissues than in adjacent tissues, consistent with the predicted results." (PMID 36118874, 2022). "However, three of the target genes, to our knowledge, are not described in relation to cancer or HBV infection (ACADSB, GABBR1, and PAPD5)." (PMID 25580300, 2014).
metabolic disorder (1 paper, 2021). "Biallelic LoF variants in the ACADSB gene cause 2-methylbutyrylglycinuria, a metabolic disorder characterized by impaired isoleucine degradation." (PMID 33727708, 2021).
ACADSB also shares sentences with these, for which no sentence is quoted: clear cell renal cell carcinoma (2 papers); colon cancer (2); adenocarcinoma (1); carnitine deficiency (1); cervical cancer (1); deafness (1); genetic disorder (1); heart failure (1); Hyperphenylalaninemia (1); metastatic prostate carcinoma (1); methylmalonic acidemia (1); muscular atrophy (1); myasthenia gravis (1); neurodevelopmental disorder (1); phenylketonuria (1); short chain acyl-CoA dehydrogenase deficiency (1); squamous cell carcinoma (1); VLCAD-deficiency (1).